VCAN (versican)
Diseases named in the same sentence as VCAN in open-access papers (continued):
Sharing a sentence is not in itself a finding about the gene and the disease.
tumor (continued). "M1 macrophage polarization was significantly reduced in tumour tissue after VCAN knockdown compared to control tumours, consistent with bioinformatic predictions." (PMID 40386063, 2025). "Recent studies have revealed a close and complex relationship between VCAN expression and tumour cell apoptosis." (PMID 40386063, 2025). "In the in vivo experiments, cell derived xenograft model were performed in nude mice using control and VCAN knockdown tumour cells." (PMID 40386063, 2025). "We aimed to examine the effect of modulating matrix cross-linkage between hyaluronan and versican using genipin on tumor cell survival, resistance, and renewal." (PMID 40656954, 2025). "We found that cGAS–STING expression in tumor cells inversely correlated with stromal expression of versican (VCAN), an immunosuppressive CAF marker, in CRC tissues." (PMID 40451897, 2025). "High levels of VCAN accumulation were common across both cohorts and staining was seen predominantly within the tumor stroma, with similar intensity distribution across the age cohorts (chi-squared, P = 0.4)." (PMID 39980836, 2025). "Overall, our findings demonstrate that MIR181A2HG‐mediated VCAN promotes M2 polarization of macrophages, thereby facilitating lymphangiogenesis in the tumor microenvironment of GC." (PMID 39823128, 2025). "ADAMTS5 major substrates are the proteoglycans aggrecan and versican, which support the structural integrity of the cartilage and the tumor microenvironment." (PMID 41381706, 2025). "VCAN, a major ECM component associated with tumor progression, was inhibited, while CDH11 was activated, highlighting ERβ’s ability to modulate cell adhesion and migration." (PMID 40647431, 2025). "Conversely, CRC tumors with high VCAN proteolysis (low total VCAN and high cleaved VCAN staining) had a 10-fold increase of CD8+ tumor-infiltrating lymphocytes (TILs) over tumors with lower VCAN proteolysis." (PMID 40361362, 2025). "Key nodes, including CHST11 and VCAN, were associated with ECM sulfation, tumor invasiveness, and immune evasion." (PMID 40507957, 2025). "Meanwhile, we examined the level of macrophage M1 polarization in tumour samples from a cell-derived xenograft mouse model, and VCAN knockdown significantly reduced macrophage M1 polarization compared to controls." (PMID 40386063, 2025). "VCAN haploinsufficiency impaired proper tumour vessel invasion, which suggests that VCAN contributes to tumour angiogenesis in stromal tissues, and the role of VCAN in angiogenesis in BCC is also a direction we need to investigate in the future." (PMID 40386063, 2025). "The cell-derived xenograft model study in nude mice showed that knockdown of VCAN in tumour cells significantly suppressed tumour size compared to control tumour cells, suggesting that VCAN is one of the important genes for tumourigenesis." (PMID 40386063, 2025). "Meanwhile, the expression of VCAN in tumour samples from BCC patients was significantly higher than that in normal skin tissues." (PMID 40386063, 2025). "In our study, we found that VCAN knockdown reduced the proliferation, migration and invasion ability of BCC and the cell-derived xenograft model study showed that knockdown of VCAN in tumour cells significantly suppressed tumour size." (PMID 40386063, 2025). "Further studies showed that inhibition of VCAN with si-VCAN reduced the relative migration and invasion rates of tumour cells compared to the control group." (PMID 40386063, 2025). "This increase in versican levels plays a critical role in the mechanisms that underpin malignant transformation and tumor progression." (PMID 40656954, 2025). "Our laboratory has established that the proteolysis of the immunoregulatory proteoglycan versican (VCAN) correlates with CD8+ tumor-infiltrating lymphocytes (TILs) in CRCs." (PMID 39980836, 2025). "VCAN is expressed in activated fibroblasts, endothelial cells, and infiltrating macrophages, linking inflammation with tumor development and progression." (PMID 39554845, 2024).
tumor (continued). "It is known that VCAN is an important agent in collagen fibrillogenesis, and its degradation can influence the reorganization of collagen fibers in the tumor microenvironment." (PMID 39682243, 2024). "Increased VCAN expression levels have been correlated to a more aggressive tumor phenotype and local BC invasiveness." (PMID 39501160, 2024). "Next, we compared these data against VCAN isoforms produced from fibroblasts (primary isolated from healthy tissues, paired tumor and surround tissue, and a human mammary fibroblast line, HMF3S), or TNBC cell lines (HCC38 and MDAMB468)." (PMID 38517140, 2024). "In order to understand, both FAP polyps and tumor samples were stained with VCAN (inflammatory marker), PDPN (CAF marker) and COL6A2 (normal fibroblast/basal lamina marker) and imaged." (PMID 39605357, 2024). "In comparison with the primary tumours, increased expression of VCAN in the stromal tissue was seen in metastatic tumours." (PMID 38791985, 2024). "VCAN was detected in the matrix of tumor emboli and within the intima and media of the small pulmonary arteries and small arterioles with tumor emboli but was only weakly expressed in the surrounding alveolar wall and not in tumor cells." (PMID 39205715, 2024). "In this case, we confirmed the expression of VEGF and PDGF in tumor cells, and VCAN in the vascular lesions, using immunohistochemical staining." (PMID 39205715, 2024). "VCAN has been identified as a biomarker for tumour metastasis and chemotherapy resistance, assisting in the monitoring of off-target effects of platinum (Pt)-based chemotherapy and facilitating timely adjustments to therapeutic strategies." (PMID 38791985, 2024). "Next, we analyzed VCAN expression levels in the tissue regions outlined during the TIP analysis: tumor core, inner and outer invasive, and stroma." (PMID 38517140, 2024). "To test this possibility, we used a transwell assay where T-cell invasion through a collagen gel supplemented with protein enriched for VCAN from tumor cells (HCC38) and fibroblasts (HMF3S) over a 24-hour timeframe." (PMID 38517140, 2024). "The overexpression of ECM proteins such as VCAN enhances tumor cell proliferation, migration, and chemotherapy resistance by creating a physical barrier that impedes drug penetration." (PMID 39554845, 2024). "Those suggest that VCAN+ TAMs enhance angiogenesis, thus possibly promoting tumor growth and infiltration." (PMID 39232806, 2024). "In vivo, we also observed a significant reversal of increased tumor metastasis in ADAMTS1-overexpressing Caki-1 cells when these cells were engineered to express shRNA targeting VCAN or the EGFR." (PMID 39333870, 2024). "For example, platelet-derived growth factor (PDGF) induces VCAN expression in arterial smooth muscle cells to facilitate the expansion of the pericellular extracellular matrix (ECM) during the tumour growth and dissemination of cancer cells." (PMID 38791985, 2024). "Comparing the pattern of expression of these VCAN isoforms in fibroblasts and tumor (HCC38) monocultures showed similar V0, V1, V3, and V4 expression as observed in tissues, but lower V2 expression." (PMID 38517140, 2024). "VCAN has the potential to foster the establishment of an inflammatory microenvironment within the tumour stroma." (PMID 38791985, 2024). "From the VCAN RNAscope staining in excluded tissues, we observed VCAN to be expressed around the tumor epithelial borders whilst in inflamed tissues VCAN+ cells were spread across the stroma." (PMID 38517140, 2024). "The proteoglycan VCAN is the most notable substrate of ADAMTS1 and was identified as a modulator of adhesion loss, cell motility, and tumor progression." (PMID 39333870, 2024). "In this study, we determined the role of VCAN in making the immunologic barrier that defines inflamed-excluded tumor phenotypes." (PMID 38517140, 2024). "Conversely in inflamed tissues, there were low levels of VCAN expression within the tumor core which increased further away from the core." (PMID 38517140, 2024).
tumor (continued). "The VCAN-HA complex can regulate the vascular and perivascular elastic structures of malignant tumours and enhance stromal cell recruitment to facilitate endothelial cell infiltration." (PMID 38791985, 2024). "The literature reports also demonstrate that TBX3 upregulates important gene targets involved in tumor development, angiogenesis and ion transport such as versican (VCAN), CD9, chromo-domain helicase DNA binding protein 1 (CHDR1) and CD86." (PMID 39358558, 2024). "The ECM, particularly the overexpression of proteins such as VCAN, contributes to increased tumor cell proliferation, migration, and protection from chemotherapy by creating a physical barrier that impedes drug penetration." (PMID 39554845, 2024). "The significant upregulation of ICAM1-AREG elucidates the promotive effects of VCAN+ TAMs on angiogenesis and tumor development." (PMID 39232806, 2024). "We also showed VCAN expression in the matrix of tumor emboli and in the intima and media of small pulmonary arteries with tumor emboli, as well as VEGF and PDGF expression in tumor cells." (PMID 39205715, 2024). "Tumor-associated macrophages (TAMs) further divided into monocyte-derived brain macrophages (Mo-TAMs) expressed monocyte markers (TGFBI, VCAN, LYZ, and CLEC12A) and cells termed as Mg-TAMs expressed microglial signature genes (TMEM119, P2RY12, and P2RY13)." (PMID 39451239, 2024). "Ligands for FFAR2 (G protein-coupled receptor 43, GPR43) inhibit the TNF-α signaling pathway, thus FFAR2 − TNF being upregulated signifies the suppressive effect of VCAN+ TAMs on anti-tumor immunity." (PMID 39232806, 2024). "VCAN then promotes mesenchymal-to-epithelial transition (MET) of metastatic tumor cells by interfering with Smad2 activation downstream of TGF-β signaling, leading to metastatic outgrowth." (PMID 37350937, 2023). "Versican is involved in the process of tumor cell metastasis and invasion in the tumor microenvironment, which is regulated by several different pathways." (PMID 37259101, 2023). "Further analysis of tumor tissue from patients at Kaohsiung Chang Gung Memorial Hospital showed that patients with LVI had significantly higher levels of VCAN." (PMID 37108649, 2023). "Tumor-associated macrophages (TAMs) upregulate PD-L1 expression of tumor cells, whereas tumor cell-secreted versican and derived exosomes induce upregulation of PD-L1 expression in TAMs, which is associated with M2 polarization of TAMs." (PMID 37822924, 2023). "The methylation intensity of N/T pairs at site four indicated a significant decrease in VCAN methylation in paired normal and tumor tissues." (PMID 37108649, 2023). "In adenocarcinoma, versican appeared to be produced by tumor-surrounding stroma cells or even the malignant cells themselves." (PMID 36831399, 2023). "The results show that among the 20 patients, 13 had lower methylation of the VCAN gene in their tumor tissues compared to normal tissues." (PMID 37108649, 2023). "For instance, VCAN can inhibit the recruitment of monocytes and neutrophils to tumor tissues, thereby reducing the anti-tumor inflammatory response." (PMID 37533434, 2023). "Among the monocyte clusters, Mono_2 cluster derived from the tumor tissue (VCAN, THBS1, and CCL20) was found to play an important immunosuppressive role." (PMID 37533434, 2023). "VCAN RNA expression was found to be significantly higher in the N1-3 group of patients with tumor lymph node staging compared to the N0 group (p < 0.05), suggesting a higher expression of VCAN in those with metastatic lymph nodes." (PMID 37108649, 2023). "In a mouse model of Lewis lung cancer(LLC), versican secreted by tumor cells promoted lung, liver, and adrenal cancer metastasis." (PMID 37259101, 2023). "Until recently, IHC was the most frequently used technique for detecting versican expression in tumor tissues." (PMID 37259101, 2023).
tumor (continued). "Our results provide evidence of VCAN’s role in tumor lymphatic metastasis and a method to measure its expression using chromatin methylation at specific loci." (PMID 37108649, 2023). "Collectively, these data support that tumor cell VCAN cooperates with myeloid IKKβ in mouse and human cancers." (PMID 36980752, 2023). "In our present study, using immunohistochemistry, versican was found to represent a constituent of the fibrous capsule and of tumor septa." (PMID 36831399, 2023). "In the tumor microenvironment, versican interacts with a variety of cell types by binding to integrins and integrin receptors, as well as other extracellular matrix components associated with the cell surface." (PMID 37259101, 2023). "Although strong evidence suggests that versican and thrombospondin play a role in tumor invasion, our study found that they were only upregulated in the LN229 cells." (PMID 37174618, 2023). "The molecular mechanism of VCAN’s anti-cancer function suggests that it can promote tumor cell migration and EMT-related molecular expression." (PMID 37108649, 2023). "Studies in vitro and in vivo have shown that VCAN regulates various cellular processes, including tumor phenotypes and properties, development of drug resistance, and tumor-stromal angiogenesis." (PMID 36842141, 2023). "VCAN depletion reduces collagen stiffness by inhibiting collagen synthesis and fibroblast proliferation, which in turn promotes tumor growth." (PMID 36759842, 2023). "In conclusion, VCAN expression was positively correlated with the tumor stage, nodal metastasis status, histologic grade, and histologic subtypes in UTUC patients." (PMID 37108649, 2023). "Versican can promote tumor cell invasion and metastasis by activating NF-κB signaling and upregulating the hyaluronic acid receptor CD44, receptor for HA mediated motility(RHAMM), and matrix metalloproteinase 9 (MMP9)." (PMID 37259101, 2023). "Tumor size-related proteins were involved in angiogenesis (VCAN, VTN, NRP1), EMT (FN1, CD44, THBS2), and translation (EIF1AX, EIF5), further indicating the biological basis of ccRCC growth." (PMID 37460463, 2023). "Ligation of TLR2 by versican has been reported to activate stromal cell populations in tumor microenvironment and subsequent inflammatory cytokine secretion." (PMID 37784035, 2023). "In the context of the tumor microenvironment, the molecular properties and biological activities of versican suggest that it has great potential as a molecular marker for tumor diagnosis and prognosis." (PMID 37259101, 2023). "The results of a comparison of tumor cell differentiation showed that VCAN RNA expression was significantly higher in the highly differentiated groups compared to the less differentiated groups (p = 0.05)." (PMID 37108649, 2023). "Mutant KRAS-IL-1β addiction is mediated via secretion of the glycoprotein versican (VCAN) by tumor cells, which inhibits the NF-κΒ kinase (IKK) β in macrophages, resulting in IL-1β release into the tumor microenvironment." (PMID 36980752, 2023). "Using a mouse model of Lewis lung cancer, we were able to demonstrate that versican and its cleavage products from matrix play an important role in the tumor microenvironment." (PMID 37259101, 2023). "FAT3 and VCAN genes are intricately involved in processes such as cell adhesion, migration, and tumor invasion, all of which constitute pivotal aspects of cancer progression and metastasis." (PMID 38086955, 2023). "Tumor-specific versican silencing and macrophage-restricted IKKβ deletion prevents myeloid NF-κB activation and metastasis." (PMID 36980752, 2023). "VCAN, a large extracellular matrix proteoglycan, is known to play role in promoting tumorigenesis and enhancing tumor progression and metastasis." (PMID 36669591, 2023).
tumor (continued). "Genes from the immune inhibitory LILRB family (LILRB1-3) are upregulated as is Versican (VCAN), which codes for epithelial to mesenchymal transition supporting proteoglycan, indicating that these cells fit the profile of tumor associated macrophages." (PMID 37532715, 2023). "VCAN protein expression has important roles in the tumor microenvironment and contributes to immune cell infiltration and extracellular matrix remodeling." (PMID 37965470, 2023). "Our results demonstrated that the expression of VCAN was positively correlated with tumor stage, nodal metastasis status, histologic grade and histologic subtypes in the BLCA database." (PMID 37108649, 2023). "Based on these results, we concluded that VCAN secreted by iCAFs was involved in the activation of stroma related pathways, thereby promoting anti-tumor therapy resistance." (PMID 36203562, 2022). "During the pathological process, ADAMTS-1 can cleave or induce the release of proangiogenic factors (IGFBP2, HB-EGF, AR) and degrade ECM components, such as versican, to facilitate tumor invasion." (PMID 36338393, 2022). "The results showed that the expression of ANGPT2, VCAN, and FosB in tumor tissue were higher than normal tissue." (PMID 36569220, 2022). "Western blot was conducted to evaluate the expression of angiopoietin-2 (ANGPT2), FosB, MS4A4A, and Versican (VCAN) in tumor tissue and normal tissue." (PMID 36569220, 2022). "Compared to normal tissues, the level of VCAN expression significantly increased in tumor tissue in STAD." (PMID 36203562, 2022). "It has been documented that VCAN is aberrantly expressed in a huge range of tumors, such as breast, ovarian, and colorectal tumors and plays a pivotal role in tumor cell invasion, metastasis, and immune infiltration." (PMID 36471693, 2022). "The increased expression of particular versican isoforms in the ECM is known to be involved in tumor cell growth, adhesion and migration." (PMID 35053843, 2022). "We assumed that VCAN shaping tumor microenvironment was related to CAFs, and conducted the pan-cancer analysis to further analyze the relationship between VCAN and CAFs." (PMID 36203562, 2022). "Signaling analysis of the tumor-derived versican-mediated TLR2 signaling identified TLR6 as necessary heterodimer and MyD88 as responsible TLR adapter." (PMID 36224342, 2022). "Another proteoglycan, the versican, which is secreted by tumor stromal fibroblasts and cancer cells, binds to HA and generates HA/versican aggregations through its N-terminal region that contains a G1 domain, composed of an immunoglobulin-like domain." (PMID 35785191, 2022). "Further investigation is required to define the roles of VCAN in tumor proliferation and invasion, either by direct influence on tumor epithelial cells, or by indirect means such as communication with activated stellate cells to affect the ECM, or both." (PMID 36923282, 2022). "From the immune perspective, VCAN has been credited with immunoregulatory functions: it acts through Toll-like receptor 2 (TLR2) to dampen antigen presentation by tumor-infiltrating dendritic cells." (PMID 36371231, 2022). "In its intact form, VCAN acts on antigen-presenting cells, dendritic cells and macrophages, to dampen tumor antigen presentation and immune responses." (PMID 36371231, 2022). "Identifying which protein isoforms of VCAN are expressed in FLC tumor epithelial cells and activated stellate cells is a critical next step toward defining the role of VCAN in FLC progression." (PMID 36923282, 2022). "In this study, we identified three immune-related genes, VEGFC, VCAN, and TNFSF, overexpressed in tumor tissues of high-risk patients and PDXY and APOLD1 upregulated in the low-risk group." (PMID 35382776, 2022). "Versican is an extracellular matrix proteoglycan that plays key roles in tumor cell invasion, metastasis, and angiogenesis." (PMID 36010993, 2022).